SPP1 (secreted phosphoprotein 1)
Diseases named in the same sentence as SPP1 in open-access papers (continued):
Sharing a sentence is not in itself a finding about the gene and the disease.
tumor (continued). "Numerous research has shown a robust association between the manifestation of SPP1 and tumor cells evolutionary progression, along with the microenvironment reprogramming." (PMID 38329443, 2024). "Pathway analysis indicated SPP1+ macrophages are associated with tumour angiogenesis, phagocytosis, lipid metabolism, and ECM interactions including the upregulation of metalloproteases." (PMID 39430099, 2024). "The potential recipients of SPP1 signalling included immune cells infiltrating tumours, cancer-associated fibroblasts, and regulatory T cells." (PMID 39149248, 2024). "In tumors, elevated expression of SPP-1 is associated with processes such as tumor growth, invasion and angiogenesis." (PMID 38627939, 2024). "Analysis of TCGA data revealed consistent findings, which suggested that SPP1+ Macs were associated with poor outcomes and that the SPP1 expression level was positively correlated with cancer stage and tumor grade in HNSCC patients." (PMID 39726047, 2024). "In turn, tumor glia promote monocyte differentiation towards pro-tumorigenic SPP1+ tumor-associated macrophages by IL-6 release." (PMID 39030280, 2024). "A recent study has suggested that the hypoxic microenvironment upregulates SPP1 expression, which results in cancer-associated fibroblasts and SPP1 macrophages forming a tumor immune barrier." (PMID 38282028, 2024). "Our study also highlights the heterogeneity of macrophage subsets within the tumor microenvironment, with SPP1+ macrophages exhibiting a distinct phenotype associated with poor phagocytic ability and enhanced angiogenic potential." (PMID 39716897, 2024). "In the context of colorectal cancer (CRC), they potentially correspond to SPP1+ tumor-associated macrophages." (PMID 38449872, 2024). "As an illustration, LYVE1+RTMs are linked to the suppression of inflammation and fibrosis in colorectal cancer (CRC), while SPP1+TAMs are linked to tumor angiogenesis in CRC, and FOLR2+TAMs support onco-fetal reprogramming of TME in HCC." (PMID 38185636, 2024). "Specifically, high levels of SPP1 expression in these TAMs are associated with a poor prognosis, as they play a role in promoting tumor progression and creating an immunosuppressive tumor microenvironment." (PMID 39727934, 2024). "Among “high-SORL1” clusters, cluster 7 was characterized by the expression of immediate early genes, SPP1, a gene associated with tumor-promoting GAMs, and ID2 involved in pro-tumorigenic polarization of myeloid cells." (PMID 38499808, 2024). "These SPP1+CCL18+ TAMs are associated with increased tumor growth and metastasis, primarily due to their high expression levels in metastasis-associated and EMT pathways." (PMID 39286635, 2024). "The expression of SPP1 in tumor-associated macrophages (TAMs) has been linked to unfavorable clinical outcomes in lung adenocarcinoma." (PMID 39727934, 2024). "Here the authors show that EGC-derived IL-6 promotes the expansion of tumorigenic SPP1+ tumor-associated macrophages, associated with worse disease outcome." (PMID 39030280, 2024). "A study showed that IL4I1 + macrophages were associated with tumor cell phagocytosis and predicted a positive prognosis for colon cancer patients, whereas SPP1 + macrophages were associated with hypoxia and necrotic tumor areas and predicted a poor prognosis." (PMID 39068459, 2024). "Differential analysis indicated that SLC16A3+ macrophages exhibit high expression of macrophage markers promoting migration, invasion and tumour angiogenesis, such as SPP1 and MMP9, as well as genes associated with glycolysis, including PKM." (PMID 39656344, 2024). "SPP1 encodes osteopontin, a phosphoprotein that mediates interactions between TAMs and tumor cells, with high expression linked to poorer survival outcomes." (PMID 39697346, 2024). "Significantly, SPP1 encoding osteopontin is closely linked to tumor cell evolution/heterogeneity and poor patient prognosis." (PMID 39122708, 2024).
tumor (continued). "SPP1 has recently gained noteworthy prominence in cancer biology due to its direct association with tumor progression and its role in inducing immune cell infiltration." (PMID 38248779, 2024). "SPP1+ TAMs significantly increase in the tumor microenvironment, are associated with poor prognosis, and promote tumor metastasis and immunosuppression." (PMID 39457004, 2024). "The DAB2+ and SPP1+ tumor-associated macrophages (TAMs) reinforce the function of FAP+ CAFs through signals such as TGF-β, PDGF, and ADM." (PMID 39239526, 2024). "SPP1 expression was correlated with the majority of immunological marker sets of monocytes, tumor-associated macrophage (TAM), M1 macrophage, M2 macrophage, Dendritic cell and Tregs in LUAD." (PMID 38329443, 2024). "Tumor regions expressing CDKN2A exhibit distinctive SPP1+ tumor-associated macrophage (TAM) infiltration and MMP7 enrichment, along with unique signaling crosstalk with adjacent areas." (PMID 38888512, 2024). "IGF2-expressing tumor cells interact with IGF1R-expressing tumor-associated erythroid cells in the patient, and tumor cells expressing SPP1 interact with tumor erythroid cells expressing ITGA4." (PMID 37894821, 2023). "The SPP1+ state acquired by macrophages co-cultured with tumoroids is highly analogous to the SPP1+ state observed in tumor-associated macrophages in vivo, relative to macrophages derived from normal adjacent tissue." (PMID 38036590, 2023). "Our analysis revealed that SPP1+ tumor-associated macrophages (TAMs) and MDSCs were the most abundant myeloid cells in the tumor microenvironment." (PMID 37475874, 2023). "Previous studies have reported that abundant infiltration of SPP1+ macrophages is frequently observed in the tumor microenvironment and is significantly associated with poor prognosis." (PMID 37265785, 2023). "We discovered a tumor microenvironmental community comprised of aggressive basal-like malignant cells, tumor-promoting SPP1+ macrophages, and myofibroblastic cancer-associated fibroblasts associated with especially poor prognosis." (PMID 37857854, 2023). "C1Q expression appears to be associated with T lymphocyte recruitment and activation whereas SPP1 expression appears to be associated with tumor growth and metastasis." (PMID 36966348, 2023). "This SPP1+ macrophage state is associated with tumor immunosuppression and poor prognosis, and SPP1 itself encodes Osteopontin, a well-established pro-oncogenic extracellular matrix (ECM) component and CD44 ligand capable of blunting T cell activation." (PMID 38036590, 2023). "We observed 3 tumor-associated macrophage (TAM) populations including a previously identified SPP1 + TAM that expressed MIF, which has been associated with alternative activation." (PMID 37633924, 2023). "The CellChat algorithm identified SPP1 as the specific signaling pathway involved in the intercellular crosstalk between tumor cells and CD8+ T cells associated with Ero1aWT tumors, which was also confirmed using the iTALK algorithm." (PMID 37769655, 2023). "PE5 showed enrichment for several cell states known to be associated with aggressive tumor behavior and poor prognosis, including basal-like tumor cells, myCAFs, and SPP1+ tumor-associated macrophages." (PMID 37857854, 2023). "SPP1 is involved in the regulation of many tumor-associated biological processes, including cell proliferation and migration, tumorigenesis and progression." (PMID 37097499, 2023). "In an anti-PD-1 treatment study involving eight HCC patients, a tumor–immune barrier structure comprising SPP1+ macrophages and cancer-associated fibroblasts was identified in non-responsive patients." (PMID 38187399, 2023). "Together, these data demonstrate that tumor-associated macrophages are primarily in an SPP1+ immunosuppressive state (particularly in MSS tumors), and tumors suppress pro-inflammatory and antigen-presenting states." (PMID 38036590, 2023).
tumor (continued). "Tumor-associated macrophages disproportionately show upregulation of SPP1 and downregulation of CD163, consistent with prior findings." (PMID 37426750, 2023). "SPP1 is a secreted chemokine-like glycophosphoprotein linked to pro-tumorigenic processes such as tumor cell invasion, proliferation, and metastasis." (PMID 37505292, 2023). "The study’s findings indicate that higher SPP1 expression in HL patients was associated with more cases of necrosis and inflammation in the tumor microenvironment." (PMID 38275392, 2023). "We found that SPP1+ tumor-associated macrophages (TAMs) and MDSCs were the most abundant myeloid cells in the microenvironment." (PMID 37475874, 2023). "In contrast to osteoblasts, overexpression of genes associated with tumor progression (SPP1, SERPINA1) was observed in CSC-like cells." (PMID 37240338, 2023). "High SPP1 expression in tumor tissue was thought to be associated with poor prognosis in many types of cancers." (PMID 37097499, 2023). "More recently, with the help of single cell typing of tumor-associated immune cells, it has been suggested that C1Q and SPP1 status best differentiate different types of tumor-associated macrophages and that these markers are also associated with prognosis." (PMID 36966348, 2023). "We performed immunofluorescence assays to detect the association between SPP1+ macrophages and tumor senescence." (PMID 37090726, 2023). "A tumor immune barrier (TIB) formed by the interaction of SPP1+ macrophages and cancer-associated fibroblasts (CAFs) was related to immunotherapy efficacy." (PMID 38347955, 2023). "A recent study showed that SPP1 + macrophages and cancer-associated fibroblasts can stimulate extracellular matrix remodeling and promote Tumor Immune Barrier (TIB) formation." (PMID 38044354, 2023). "Further, single molecule fluorescent in situ hybridization confirmed the expression of SPP1 in tumor-associated macrophages in CRC tissue." (PMID 38036590, 2023). "Epithelial and macrophage-secreted SPP1 activated tumor-associated inflammation, and interestingly, the epithelial SPP1 promoted early tumorigenesis by fostering the mutant KrasG12D-expressing cells." (PMID 37513116, 2023). "IHC revealed that SPP1 expression is significantly associated with tumor type, stage, grade and smoking status." (PMID 38067407, 2023). "Our study suggests that SPP1 gene expression has a tight association with various immune-related cells in the tumor microenvironment of PSCC." (PMID 38111044, 2023). "Accumulating evidences indicated that SPP1 plays an important role in several tumor-associated processes, such as proliferation, invasion, migration, angiogenesis, and metastasis." (PMID 35067176, 2022). "There has been no previous report on SPP1 and GC, but this study, based on bioinformatics, first found that SPP1 is a risk factor for GC prognosis, and its mechanism of tumor action needs further study and demonstration." (PMID 35174205, 2022). "SPP1 is an integrin-binding glycol-phosphoprotein whose overexpression exerts diverse tumor-associated functions such as proliferation, invasion, migration, angiogenesis, and metastasis." (PMID 35875097, 2022). "The secreted phosphoprotein 1 (SPP1) is an integrin-binding phosphorylated glycoprotein that has been reported to play important roles in several tumor-associated processes, including proliferation, invasion, migration, angiogenesis, and metastasis." (PMID 36036011, 2022). "FOXE1 is a transcription factor with poorly defined function in senescence, whereas SPP1 encodes osteopontin, a secreted stromal protein involved in tumor growth." (PMID 35883188, 2022). "Intriguingly, ectopic MYC in MET tumours increases expression of the Mki67 proliferation marker, and switches them into loss of Afp, Spp1, Gpc3, Epcam accompanied by an increase in Hgma1, Vim, and Hep-Par1 levels." (PMID 36433941, 2022).
tumor (continued). "As a major mediator of tumor-associated inflammation, SPP1 has been proven to be related to enzalutamide resistance by activating the PI3K/AKT and ERK1/2 signaling pathways in CRPC, and promoting the invasion and metastasis of CRPC." (PMID 36389722, 2022). "Except for SPP1+TAMs, all TAMs associated with tumor progression were enriched in dMMR, while GNLY+ Monolike Macros with the anti-tumor immune function were abundant in pMMR." (PMID 36232318, 2022). "We further validate the top ligand-receptor interaction pairs (i.e., LGALS9-SLC1A5 and SPP1-PTGER4 between tumor cells and macrophages) associated with unique transcriptome in additional 542 HCC patients." (PMID 36476645, 2022). "Macro-2 was separated from the other macrophage clusters by overexpressing TREM2 and SPP1, two genes that have been associated with tumor angiogenesis and immune checkpoint therapy." (PMID 36180422, 2022). "The SPP1 gene (osteopontin, secreted phosphoprotein 1) encodes a protein with several activities, including bone remodeling, adhesion, tumor invasion, and metastasis." (PMID 36303551, 2022). "In GBM, miR-181a-5p is downregulated and functions as a tumor suppressor miRNA that inhibits the translation of oncogenic proteins that are linked to tumor progression such as osteopontin (SPP1)." (PMID 35371977, 2022). "The survival analysis indicated that the group with a high predicted SPP1 target signature was associated with poor prognosis, supporting the tumor-promoting characteristics of SPP1." (PMID 36612160, 2022). "All these results suggest that the dysregulated transcription of SPP1 favours the loss of cell adhesion that allows tumour cells to dissociate from the primary tumour mass, favouring tumour cell invasion and dissemination." (PMID 36077612, 2022). "According to previous studies, the SPP1 + TAMs are closely related to cancer-associated endothelial cells and fibroblasts, thus modulating the tumor microenvironment." (PMID 36008393, 2022). "Infiltration levels of SPP1+CD68+ tumor-associated macrophages (TAMs) were examined by dual immunofluorescence (IF) staining in 264 resected ICC samples." (PMID 35558087, 2022). "Another key role of SPP1 is associated with immune response, regulating host immunity, and being associated with increased cell proliferation by preventing tumour cell apoptosis." (PMID 36077612, 2022). "Extending the findings in previous work 13, we observed two subpopulations of SPP1+ tumor-associated macrophages (TAMs) characterized by high phagocytosis (SPP1+ CD209high TAMs) and angiogenesis (SPP1+ CD209low TAMs) abilities." (PMID 36438481, 2022). "SPP1 overexpression was positively associated with tumor size, nodal status, and histological grade of GAC patients." (PMID 34367279, 2021). "The overexpression of the SPP1 is associated with the growth and stage of LC, tumour angiogenesis and lymph node metastasis, and represents a more aggressive NSCLC type." (PMID 33626243, 2021). "We identified SPP1+ tumor-associated macrophage (TAM) subpopulation potentially enhanced epithelial–mesenchymal transition (EMT) by interaction with cancer cells through paracrine pattern." (PMID 34676217, 2021). "Our pseudotime analysis suggested that global methylation level affected the differentiation of tumor cells and that SPP1 was associated with methylation level and patient prognosis." (PMID 34857857, 2021). "Cells in Mac_0 were characterized by expression of complement-related genes (C1qa, C1qb, C1qc) and cytokines (Spp1, Ccl12), while cells in Mac_1 expressed higher levels of several tumor-associated macrophage-related genes such as Arg1, Cebpb, and Ier3." (PMID 34030676, 2021). "Upregulation of SPP1 in tumor tissue and plasma was found to be associated with poor prognosis in patients in many kinds of cancer." (PMID 34721759, 2021). "OPN encoded by the SPP1 gene has been shown to play critical roles in tumor progression by interacting with different receptors, such as integrin and CD44 receptors." (PMID 34805184, 2021).
tumor (continued). "High SPP1 expression in the tumour tissue was associated with inferior survival in a previous study with small sample size." (PMID 33626243, 2021). "APOE, APOC1, and SPP1 were highly expressed in tumor-associated macrophages resulting in anti-inflammatory macrophage phenotypes." (PMID 34697289, 2021). "In this study, we showed that the SPP1 expression is significantly higher in LUAD tumor tissues and in patients with EGFR mutation." (PMID 34178613, 2021). "Secreted phosphoprotein 1 (SPP1) is a cardinal mediator of tumor-associated inflammation and facilitates metastasis." (PMID 34721759, 2021). "Last but not least, our study laid the foundation for detailed studies of the correlation between SPP1 and the tumor-associated immune microenvironment." (PMID 35058964, 2021). "Expression of SPP1 was associated with the global methylation status of tumor cells and with patient prognosis." (PMID 34857857, 2021). "SPP1 plays an important role in several tumor-associated processes, including proliferation, invasion, migration, angiogenesis, and metastasis 11-13." (PMID 33052224, 2020). "For example, SPP1 is also expressed by endothelial and smooth muscle cells and loss of stroma-derived SPP1 led to enhanced tumor progression in mice." (PMID 33585455, 2020). "The SPP1 expression increased the risk of recurrence with an odds ratio (OR) of 2.50 (95% confidence interval [CI]; 1.30–4.82), after adjustment for tumour grade, HER 2 status and other treatments to OR 3.62 (95% CI; 1.45–9.07)." (PMID 31996744, 2020). "Clinically, SPP1 expression level in tumor tissue and plasma is associated with poor prognosis and survival in patients with PCa." (PMID 31620371, 2019). "SPP1 is associated with aggressiveness of cancer, increases in tumor promoting inflammation and activates invasion and metastasis, which is in perfect agreement with our findings." (PMID 30647841, 2018). "The levels of SPP1 mRNA are up-regulated in many malignant cancer tissues, and elevated levels of SPP1 in patients’ tumour tissue and blood are associated with poor prognosis." (PMID 28030801, 2017). "We also identified Iroquois Homeobox 2 (IRX2) as the master regulators for an expression of SPP1-encoded osteopontin, a secreted stromal driver for tumor growth that is overexpressed by both RS and SIPS fibroblasts." (PMID 28105936, 2016). "SPP1-encoded osteopontin, a secreted stromal driver for tumor growth, is overexpressed by both RS and SIPS fibroblasts." (PMID 28105936, 2016). "BaP induced lung epithelial cells to secret CXCL13, which recruited tumor-associated macrophages (TAMs) and induced SPP1 production." (PMID 26565418, 2015). "In terms of an association with cancer, SPP1 has been shown to promote the growth of different tumours." (PMID 25884485, 2015). "Interestingly, fibroblasts from KPTN tumors were enriched with populations (clusters 6–8) that highly expressed Acta2, Spp1, and Sdc1, which were associated with a tumor-promoting fibroblast phenotype." (PMID 41480763, 2026). "Functionally, VISTA deficiency is linked to a shift in tumor-associated macrophages (TAMs) from an immunosuppressive phenotype marked by secreted phosphoprotein 1 (SPP1), to one enriched for C-X-C motif chemokine ligand 9 (CXCL9), indicative of a pro-inflammatory state." (PMID 41776161, 2026). "This study addresses the limitations of the traditional M1/M2 binary classification for tumor-associated macrophages (TAMs) in non-small cell lung cancer (NSCLC) by introducing a NSCLC-specific functional framework based on the CXCL9/SPP1 (CS) expression ratio." (PMID 42079623, 2026). "It further identifies PLXDC1+ PSCs near aggressive LRRC15+ cancer‐associated myofibroblasts and SPP1+ macrophages, forming a desmoplastic and immunosuppressive tumor niche that promotes CD8+ T cell exhaustion, contributing to poor immunotherapy outcomes in pancreatic cancer." (PMID 40091495, 2025).